CD8A (CD8 subunit alpha)
Diseases named in the same sentence as CD8A in open-access papers (continued):
Sharing a sentence is not in itself a finding about the gene and the disease.
Obesity (345 papers, 2010 to 2026). Accumulation of substantial excess body fat. "In addition, splenic CD8+ T cells were used to reconstitute CD8a−/− KO mice fed with a HFD, which aggravated insulin resistance induced by obesity." (PMID 33413697, 2021).
leukemia (341 papers, 2005 to 2026). A malignant (clonal) hematologic disorder, involving hematopoietic stem cells and characterized by the presence of primitive or atypical myeloid or lymphoid cells in the bone marrow and the blood. "It has been found that antigens from circulating leukemic cells are primarily captured and cross-presented by a subset of splenic cDCs, named CD8α+ DCs, mediating leukemia antigen recognition by antigen-specific CD8+ T cells in vivo." (PMID 38459166, 2024). "Here, we discovered that CD8α– NK cells had improved control of leukemia in xenograft models compared with CD8α+ NK cells, likely due to an enhanced capacity for proliferation." (PMID 38805302, 2024). "In AML mouse models, leukemia antigen presentation by immature antigen-presenting cells or splenic CD8a+ dendritic cells (DCs) have respectively induced deletional T cell tolerance and CD8+ T cell tolerance." (PMID 39682161, 2024). "In a mouse model of AML, deletional CD4+ and CD8+ T cell tolerance induction is attributed to leukemia antigen presentation by immature antigen-presenting cells (DCs) or splenic CD8α+ dendritic cells." (PMID 36081495, 2022). "The control anti-CD19 CAR (CD19 CAR) thus resembles tisagenlecleucel (fmc63scFv-CD8a spacer/TM-41BB-z), which is in clinical use against leukemia." (PMID 35860008, 2022). "CD8α+ NK cells exhibit greater cytotoxic function against leukemia cells." (PMID 39087476, 2024). "CD8α– NK cells, which could remain CD8α– or become iCD8α+, mediated superior tumor control in leukemia xenograft mouse models, likely due to their enhanced capacity for expansion in vivo." (PMID 38805302, 2024). "However, a direct comparison of CD22-targeting CAR bearing a CD8α hinge or a CD28 hinge showed that CD8α exhibited more significant cytotoxicity against a decreased antigen density CD22 positive leukemia." (PMID 37444586, 2023). "We previously demonstrated in leukemia-bearing mice that cross-presentation of a leukemia-specific antigen by splenic CD8α+ type 1 conventional dendritic cells (cDC1s) induced the deletion of a CD8+ T cell population expressing a high-affinity T cell receptor (TCR; referred to as TCR2C)." (PMID 34758311, 2021). "We previously showed that leukemia antigen recognition by and deletion of TCR2C was mediated by antigen cross-presenting splenic CD8α+ cDC1s." (PMID 34758311, 2021). "CD8α+ and DN iNKT cells most frequently expressed CD56, CD161 and NKG2D and most potently killed CD1d+ cell lines and primary leukemia cells." (PMID 22174854, 2011). "Mature CD8α+ cDC1s are recognized for suppressing graft-versus-host disease (GvHD) while promoting graft-versus-leukemia (GvL), however pre-cDC1s have not previously been investigated in the context of alloreactivity or anti-tumor responses." (PMID 35980974, 2022). "CD8α expression on donor NK cells was associated with a lack of therapeutic responses in patients with leukemia in prior studies, thus, we hypothesized that CD8α may affect critical NK cell functions." (PMID 38805302, 2024).
glioblastoma (324 papers, 2004 to 2026). The most malignant astrocytic tumor (WHO grade IV). "In glioblastoma, LAG-3 is expressed along with CD8A, suggesting that LAG-3 targeted therapy in glioblastoma with sufficient CD8+ T cell infiltration may be hopeful." (PMID 37077370, 2023).
prostate carcinoma (316 papers, 2001 to 2026). A carcinoma that arises from epithelial cells of the prostate gland. "Moreover, IFN-stimulated genes are significantly associated with CD8A and CD3D expression, indicating the correlation between the IFN signaling and T cells infiltration in prostate cancer samples." (PMID 35836810, 2022). "The sustained anti-tumor effect of CD8+ T cells after drug withdrawal was likely related to the formation of TLS, as indicated by a large number of BrdU+ CD8+ T cells were present in TLS and a positive correlation between TLS score and CD8A expression in BAY1082439-treated TEN-null prostate cancer." (PMID 38690273, 2024). "We synthesized the B7-H3 scFv sequence based on 8H9 clone and constructed the second-generation B7-H3 CAR containing CD8α transmembrane region, CD28 intracellular costimulatory domain, and CD3ζ intracellular signaling domain after confirming that B7-H3 is highly expressed in prostate cancer." (PMID 37149721, 2023).
psoriasis (291 papers, 2005 to 2026). An autoimmune condition characterized by red, well-delineated plaques with silvery scales that are usually on the extensor surfaces and scalp. "To investigate, whether extrinsic factors influence CD8α cDC1 differentiation we used a mouse model with deletion of c-Jun/JunB restricted to keratinocytes (c-Jun/JunBΔ/ΔK5-CreER) that results in a psoriasis-like skin inflammation." (PMID 33758366, 2021).
cervical carcinoma (284 papers, 2002 to 2026). A carcinoma arising from either the exocervical squamous epithelium or the endocervical glandular epithelium. "The results showed that PD-L1 expression in cervical cancer was positively correlated with the infiltration of CD8+ T cells and the expression of CD8A." (PMID 38869633, 2024). "Tumor microenvironment immune types (TMIT) have been classified into four categories, with cervical cancer specified as TIMT I with high expression of PD-L1 and CD8A/cytolytic activity (CYT), according to the classification criteria of TMIT by expression of PD-L1 and CD8A/CYT." (PMID 36313730, 2022).
colitis (276 papers, 2008 to 2026). Inflammation of the colon. "These Th2-derived CD4+CD8α+ T cells were recovered from the primary recipient mice and subsequently transferred into secondary immunodeficient hosts, where they prevented colitis development induced by pathogenic CD4+CD45RBhi T cells." (PMID 23844100, 2013). "We could recently show that activation of myeloid PI3K signaling drives immunosuppressive CD8α+DCs that impair antitumor T cell responses in a model of colitis-associated colorectal cancer." (PMID 35514976, 2022). "Studies indicate that CD4+CD8α+ IELs protect against autoimmune colitis in a food allergy model, and exacerbated colitis is observed on re-encountering the cognate or bacterial antigen; however, their precise role in the intestine is unclear." (PMID 36353619, 2022). "The HLA-B27+ transgenic arthritic/colitis rat model persistently developed SpA-like features even after the depletion of CD8+ T cells with either anti-CD8α monoclonal antibodies or CD8α knockout." (PMID 34095174, 2021). "The most important finding in this study is the ability of TCRαβ+CD8α+ IELs to suppress the onset of colitis when transferred into LTAC mice." (PMID 26132627, 2015). "Remarkably, transfer of TCRαβ+CD8α+ IELs from wild-type mice ameliorated colitis in Lck-cre:TAK1fl/fl mice." (PMID 26132627, 2015). "From the point of view of amelioration of the disease, it is remarkable that transfer of TCRαβ+CD8α+ IELs restrained spontaneous colitis, consistent with previous reports that the cells have an ability to suppress gut inflammation." (PMID 26132627, 2015). "It was shown that both B-cells and CD8a+ T-cells expressing Galphai-2 were required to prevent the onset of disease in the CD4+CD45RB+ T-cell transfer colitis model, but the precise mechanism behind this remains unclear." (PMID 35163775, 2022). "CD4+CD8A+ T cells in the intestine expressed IL10, which is essential for the inhibition of colitis." (PMID 36353619, 2022). "Previous work in a mouse model of colitis determined that CD11c+ CD8+ Tregs are CD8α+ CD103+ NK1.1- in the small intestine, but CD8α- CD103- NK1.1+ in the colon." (PMID 27119555, 2016). "Surprisingly, when TCRαβ+CD8α+ IELs were transferred into LTAC mice, we noticed a significant amelioration of colitis." (PMID 26132627, 2015). "Further investigation of FADD on mucosal immunology seems meaningful since the influence on CD8α+TCRγδ+ subset mediated by FADD might be involved in the initiation and/or perpetuation of colitis." (PMID 30250469, 2018). "The decreased CD8α+TCRγδ+ T cells will take responsibility for the reduced homeostasis in intestinal mucosal immune system, so FADD-DN mice show more severe inflammation in DSS-induced colitis model." (PMID 30250469, 2018). "Transfer of TCRαβ+CD8α+ IELs but not any other T cell subsets such as conventional CD8+ T or NKT cells ameliorated colitis in Lck-cre:TAK1fl/fl mice." (PMID 26132627, 2015). "Collectively, these data indicated that the lack of TCRαβ+CD8α+ IEL in the intestinal epithelial layer led to the pathogenesis of colitis in LTAC mice." (PMID 26132627, 2015). "While the DCs subsets studied did not appear to significantly express TNF-α, there were significantly more numbers of MLN and PP CD8α+ DCs and only PP-derived CD8α- DCs that expressed IFN-γ from mice with live Mycobacteria-enhanced colitis, than compared to other groups." (PMID 18533024, 2008).
lupus (264 papers, 2006 to 2026). "The expression of markers of T cells (CD4, CD8α), B cells (CD19) and macrophages (CD68) was elevated in PVAT from lupus mice." (PMID 37006244, 2023). "Of note, the analysis of non-TFH CD4 + T helper cells (defined as CD45+ CD19– TCRβ+ CD8α– CD4+ CD44+ CXCR5 – cells) revealed that basophil depletion in lupus-like models impacted only the TH2 cell compartment in both mouse models." (PMID 38649353, 2024). "Nevertheless, we observed a slightly but significantly higher percentage of CD40-positive cells in CD8α+ DCs from lupus-prone mice than in non-autoimmune mice at a young age." (PMID 16507174, 2006). "We used a protocol that maximizes DC yield to analyze the characteristics of the three major DC subsets, namely myeloid, CD8α+, and plasmacytoid; and to compare lupus-prone mice with multiple age-matched non-autoimmune mice." (PMID 16507174, 2006). "However, the acceleration in mortality in BXSB.Yaa mice rendered deficient in H-2K/D, Tap1, or CD8α was not as profound as that observed in β2m° BXSB.Yaa mice, suggesting that more than one mechanism likely accounts for the protective effect of β2m in lupus." (PMID 23531237, 2013).
lung adenocarcinoma (254 papers, 2015 to 2026). A carcinoma that arises from the lung and is characterized by the presence of malignant glandular epithelial cells. "In support of this notion, assessment of only patients with late-stage lung adenocarcinoma demonstrated a survival advantage for low CD8a expression." (PMID 40553564, 2025). "CD8A andIL2RB expression levels are markedly higher in advanced lung adenocarcinoma, the most prevalent histological type of NSCL, indicating its predictive function in NSCLC." (PMID 38379417, 2024). "The analysis revealed that CCL5 expression is positively correlated with CD8A expression in three cancer types (breast invasive carcinoma, lung adenocarcinoma, and colon adenocarcinoma)." (PMID 36352411, 2022). "Besides, results elucidated that CD8A expression levels were closely linked to the tumor stage, as evident by higher expression levels in the early stage than in advanced stages of COAD and lung adenocarcinoma (LUAD)." (PMID 36035168, 2022). "An automated eight-color mIF panel was evaluated to study the TME using seven antibodies, including cytokeratin 19, CD3e, CD8a, CD4, PD-1, PD-L1, F4-80 and DAPI, then was applied in six mice lung adenocarcinoma samples." (PMID 38877529, 2024). "In the analysis of the TCGA dataset, we found that the expression of IL17A was significantly positively correlated with the expression of CD8A in invasive breast carcinoma (BRCA), liver hepatocellular carcinoma (LIHC), and ovarian serous cystadenocarcinoma (OV) in lung adenocarcinoma in TCGA." (PMID 35459193, 2022). "Moreover, high expression of FLT3LG was significantly positively correlated with increased infiltration of multiple immune cells, including T cells and natural killer (NK) cells, in lung adenocarcinomas, as well as the expression of several immune cell markers, such as CD4 and CD8a." (PMID 40329265, 2025).
type 1 diabetes (252 papers, 2007 to 2026). "Our results showed that IRF4 expression was up-regulated in NOD mice and correlated with the increased levels of CD4+CD8α− DCs, suggesting that IRF4 may be involved in abnormal DC functions in type 1 diabetes in NOD mice." (PMID 21647406, 2011).
multiple sclerosis (250 papers, 2007 to 2026). A progressive autoimmune disorder affecting the central nervous system resulting in demyelination. "Interestingly, in rats CD8α+ monocytes and Mφ are found at sites of tissue damage in immune-complex mediated glomerulonephritis, arthritis, tumor, experimental allergic encephalomyelitis (a model of multiple sclerosis), and ischaemia-reperfusion injury." (PMID 17678538, 2007).
vitiligo (249 papers, 2005 to 2026). Generalized well circumscribed patches of leukoderma that are generally distributed over symmetric body locations and is due to autoimmune destruction of melanocytes. "Highly significant changes in the levels of CD4+CD8α-, CD4-CD8α+ and CD4+CD8α+ T cells were detected over time in growing feathers of vitiligo-expressing Smyth chickens (P = 0.0003, < 0.0001 and < 0.0001, respectively)." (PMID 38720888, 2024). "Highly significant, positive correlations between the D-score of TCR-β2 and infiltrating αβ2 T (P < 0.0001), CD4-CD8α+ (P < 0.0001) and CD4+CD8α+ (P = 0.0003) cells were found in data obtained from vitiligo-expressing Smyth chickens." (PMID 38720888, 2024).
breast tumors (244 papers, 2012 to 2026). "Remarkably, immune–gene expression signatures reflecting an increased recruitment of activated NK and T cells in breast tumors (i.e., CD8A, CD247, CD3D, GZMA) have been shown to be predictive of clinical benefit from preoperative and adjuvant trastuzumab-based treatment." (PMID 29181007, 2017). "By analyzing publicly available spatial transcriptomics data, we confirmed co‐expression of CD8A and ADRB2 within breast tumors." (PMID 40397381, 2025).
bladder cancer (239 papers, 2006 to 2026). "The authors analyzed samples from patients with advanced bladder cancer treated with immunotherapy and observed that low levels of CD8A expression were associated with resistance to immunotherapy." (PMID 38396726, 2024). "CD8A expression is highly associated with tumor microenvironment characteristics and tumor mutation burden, which partially explain CD8A as a prognostic and immunotherapy predictive biomarker in bladder cancer." (PMID 36230788, 2022). "In this way, an MRI-based radiomics signature has the potential to preoperatively predict the expression of CD8A, thereby contributing to the preoperative prediction of prognosis and immunotherapeutic susceptibility in bladder cancer." (PMID 36230788, 2022). "Furthermore, in bladder cancer patients, risk scores were inversely linked with the expression levels of immune marker genes (CD8A, CD80, etc.)and immune activation‐related genes (IL6, IFNG, etc.)." (PMID 37771276, 2023). "CD8A expression positively correlates with CD8+ T cell and M1 macrophage infiltration, and high-density CD8+ T cells in bladder cancer patients are associated with better immune therapy response and improved prognosis." (PMID 38279987, 2024). "In bladder cancer, as a new protective gene, CD8A presented the highest correlation with T cells and M1 macrophages." (PMID 37325556, 2023). "Based on RNA expression data, we found that among T cytotoxic pathway-related genes, CD8A is a novel protective gene in bladder cancer." (PMID 36230788, 2022). "We aimed to investigate the clinical predictive value of CD8A in prognosis and tumor microenvironment (TME) and preoperatively predict the expression of CD8A using radiogenomics in bladder cancer (BCa)." (PMID 36230788, 2022). "The results revealed a significant positive correlation between CXCR6 expression and CD8A, effector T cell signature, and CD274 (PD-L1) in bladder cancer, suggesting that CXCR6 may hold potential as a predictive biomarker for immunotherapy response." (PMID 39588301, 2024).
liver cancer (234 papers, 2014 to 2026). An epithelial or non-epithelial malignant neoplasm that arises from the liver. "We detected the expression of CYPJ, CD86 (a marker for M1 TAMs), CD163 (a marker for M2 TAMs), CD8 (a marker for CD8+ T cell), and EpCAM (a marker for tumor cells) in tissues from liver cancer patients using the mIHC method." (PMID 40520002, 2025). "When patients were divided into ‘high’ and ‘low’ CD8 expression based on the top 20% value of CD8A, we observed that elevated CD8A expression was associated with better patient survival in the TCGA liver cancer database." (PMID 37997519, 2023). "Next, we examined the clinical significance of CD8A expression in liver cancer." (PMID 37997519, 2023). "The higher positive expression of CD8A and CXCL6 was found in both LIHC tissues and most human liver cancer cell lines." (PMID 37325556, 2023). "RT-qPCR results indicated higher positive expression of CD8A and CXCL6 in both LIHC tissues and most human liver cancer cell lines." (PMID 37325556, 2023). "Through the experiment, it was found out that CD8A and CXCL6 showed higher positive expression in both LIHC tissues and most human liver cancer cell lines, which implied that both PRDEGs might be potential biomarkers for the diagnosis and treatment of LIHC." (PMID 37325556, 2023).
asthma (222 papers, 1995 to 2026). "It was found that CD8A was mainly enriched in Rheumatoid arthritis, Asthma, Cholesterol metabolism, etc." (PMID 36505419, 2022). "A particular interesting case is the differential methylation and expression of CD8A in asthma that was counterintuitively attributed to macrophages." (PMID 33076907, 2020). "CD8α+ DC can be found in murine lymphoid organs and sometimes can play a regulatory role in asthma by enhanced cross-priming CD8+ T cells [reviewed in Ref." (PMID 28670318, 2017). "CD8α+ DCs enhance cross-priming of CD8+ T cells redirecting the immune response in asthma away from Th2 response, as shown here with decrements of IL-4 and IL-13 levels, decreased number of eosinophils." (PMID 28670318, 2017). "These three phenotypes of pDCs play different roles in asthma, with CD8α+β- and CD8α+β+ pDCs contributing to tolerance by inducing regulatory T cells in experimentally induced allergic asthma, whereas CD8α-β- pDCs can induce and potentiate allergic lung inflammation." (PMID 39530090, 2024). "There was a significant positive correlation between IL15 expression and markers of T cells, including CD3E and CD8A but did not include CD4, suggesting the presence of nested CD8+ T cells in the airways of patients with asthma as previously observed." (PMID 40048261, 2025).
metastatic melanoma (217 papers, 2005 to 2025). A melanoma that has spread from its primary site to another anatomic site. "Among them, CD8A, SOX2, TYR, CXCL10 and ICAM1 had the most interaction with other proteins associated with metastatic melanoma." (PMID 39820173, 2025). "In summary, this study reports the promising association of individual immunotherapy panel markers CD274, PDCD1LG2, CD8A, IRF1 and a combined L1/L2 score (CD274 & PDCD1LG2) with improved immunotherapy outcome in metastatic melanoma." (PMID 31533832, 2019). "In fact, in metastatic melanomas, BMAL1 expression exhibited a strong positive correlation with the expression of dendritic cell markers, T-cell markers CD4 and CD8A, and T-cell activation/differentiation markers." (PMID 29946530, 2018).